OR4C12 (olfactory receptor family 4 subfamily C member 12)
Description:
Acts as a receptor for R-(-)-carvone in pancreatic cells, initiating signaling pathways involving GNAS, elevated intracellular Ca(2+), and increased cAMP levels. Upon activation, promotes glucose-stimulated insulin secretion.
Synonyms: OR11-259
Tractability: Antibody: its Gene Ontology location is reachable by antibodies, with high confidence; UniProt places it where antibodies can reach, with medium confidence; UniProt predicts a signal peptide or a membrane-spanning region.
Gene: Protein-coding gene on chromosome 11 (49,981,473 to 49,982,535, reverse strand). Ensembl gene ENSG00000221954.
Subcellular location: Cell membrane
Pathways (Reactome):
Sensory Perception: Expression and translocation of olfactory receptors; Olfactory Signaling Pathway
Gene Ontology:
Molecular function: olfactory receptor activity; G protein-coupled receptor activity
Biological process: glucose homeostasis; detection of chemical stimulus involved in sensory perception of smell; G protein-coupled receptor signaling pathway
Cellular component: plasma membrane; membrane
Genetic constraint (gnomAD): Loss-of-function variants: 11 observed, 12.19 expected, observed/expected ratio (o/e) 0.9, 90% interval 0.57 to 1.49. The upper end of that interval is the gene's LOEUF score, 1.49, which puts it in group 6 of 6, group 1 being the genes least tolerant of losing a copy. Missense variants: 368 observed, 339.49 expected, observed/expected ratio (o/e) 1.08, 90% interval 1 to 1.18. Synonymous variants: 126 observed, 123.16 expected, observed/expected ratio (o/e) 1.02, 90% interval 0.88 to 1.19.
Homologues: Orthologues: chimpanzee OR4C12 (98% identical), dog OR4C12C (84% identical), mouse Or4c12 (83% identical), rat Or4c12 (83% identical), mouse Or4c12b (82% identical). Paralogues in human: OR4C13 (66% identical), OR4C46 (65% identical), OR4C5 (62% identical), OR4C6 (61% identical), OR4C3 (60% identical), OR4C45 (60% identical), OR4A47 (60% identical), OR4A15 (59% identical), OR4C15 (59% identical), OR4C11 (57% identical), OR4B1 (57% identical), OR4S2 (57% identical), and 116 more.